TPP1 (tripeptidyl peptidase 1)
Description:
Lysosomal serine protease with tripeptidyl-peptidase I activity. May act as a non-specific lysosomal peptidase which generates tripeptides from the breakdown products produced by lysosomal proteinases. Requires substrates with an unsubstituted N-terminus.
Synonyms: TPP-1; LPIC; CLN2; GIG1; SCAR7
Tractability: Small molecule: it has a high-quality binding pocket. Antibody: UniProt predicts a signal peptide or a membrane-spanning region. PROTAC: its protein half-life has been measured.
Target class: Enzyme; Hydrolase
Gene: Protein-coding gene on chromosome 11 (6,612,768 to 6,619,448, reverse strand). Ensembl gene ENSG00000166340.
Subcellular location: Lysosome; Melanosome
Pathways (Reactome):
Cellular responses to stimuli: XBP1(S) activates chaperone genes
Gene Ontology:
Molecular function: endopeptidase activity; lysophosphatidic acid binding; peptidase activity; protein binding; serine-type peptidase activity; sulfatide binding; tripeptidyl-peptidase activity; peptide binding; serine-type endopeptidase activity
Biological process: bone resorption; epithelial cell differentiation; nervous system development; peptide catabolic process; protein localization to chromosome, telomeric region; proteolysis; central nervous system development; lipid metabolic process; lysosome organization; neuromuscular process controlling balance; protein catabolic process
Cellular component: extracellular exosome; Golgi apparatus; lysosome; melanosome; membrane raft; recycling endosome; lysosomal lumen
Genetic constraint (gnomAD): Loss-of-function variants: 43 observed, 71.07 expected, observed/expected ratio (o/e) 0.61, 90% interval 0.47 to 0.78. The upper end of that interval is the gene's LOEUF score, 0.78, which puts it in group 3 of 6, group 1 being the genes least tolerant of losing a copy. Missense variants: 671 observed, 748.61 expected, observed/expected ratio (o/e) 0.9, 90% interval 0.84 to 0.95. Synonymous variants: 272 observed, 296.97 expected, observed/expected ratio (o/e) 0.92, 90% interval 0.83 to 1.01.
Gene-disease validity (ClinGen):
ClinGen rates the evidence that TPP1 causes each of these diseases.
neuronal ceroid lipofuscinosis (autosomal recessive): Definitive.
Homologues: Orthologues: chimpanzee TPP1 (99% identical), macaque TPP1 (98% identical), rabbit TPP1 (91% identical), pig TPP1 (90% identical), dog TPP1 (90% identical), guinea pig TPP1 (88% identical), mouse Tpp1 (88% identical), rat Tpp1 (87% identical), tropical clawed frog tpp1 (61% identical), zebrafish tpp1 (60% identical).
Diseases named in the same sentence as TPP1 in open-access papers:
TPP1 is named in the same sentence as 183 diseases in open-access papers, as found by Europe PMC text mining. Sharing a sentence is not in itself a finding about the gene and the disease. The quoted sentences say what the papers report.
neuronal ceroid lipofuscinosis (41 papers, 2010 to 2025). "This missense variant has been shown to impair TPP1 function in individuals with neuronal ceroid lipofuscinosis." (PMID 40507848, 2025). "Mutations in TPP1 are the cause of another type of neuronal ceroid lipofuscinosis, CLN2, underlining its importance for lysosomal homeostasis and function." (PMID 39033178, 2024). "Classic late infantile neuronal ceroid lipofuscinosis (CLN2 disease) is caused by a deficiency of tripeptidyl-peptidase-1." (PMID 35106137, 2021). "Mutations in CLN2 encoding tripeptidyl-peptidase 1 (TPP1) are the basis of late-infantile neuronal ceroid lipofuscinosis (LINCL or CLN2)." (PMID 34451881, 2021). "Mutations in TPP1 cause an autosomal recessive neurodegenerative lysosomal storage disorder known as neuronal ceroid-lipofuscinosis (NCL)." (PMID 29554876, 2018). "Mutations in tripeptidyl peptidase 1 (TPP1) have been associated with late infantile neuronal ceroid lipofuscinosis (NCL), a neurodegenerative disorder." (PMID 28546289, 2017). "Classical late-infantile neuronal ceroid lipofuscinosis (LINCL) is a recessively inherited lysosomal storage disease (LSD) resulting from mutations in the gene that encodes the lysosomal protease tripeptidyl peptidase I (TPP1)." (PMID 22792360, 2012). "Interestingly, mutations in TPP1 are one of the causes of late infantile neuronal ceroid lipofuscinosis, a fatal neurodegenerative disease associated with altered externalizing behavior alongside neurodegeneration." (PMID 35513368, 2022). "Late-infantile neuronal ceroid lipofuscinosis is a fatal neurodegenerative disease of children caused by mutations resulting in loss of activity of the lysosomal protease, tripeptidyl peptidase 1 (TPP1)." (PMID 29408933, 2018). "Furthermore, we also show that one of the most common disease causing TPP1 gene variants in classic late infantile neuronal ceroid lipofuscinosis may also be amenable to splicing modulation using similar substances." (PMID 34831035, 2021). "Late infantile neuronal ceroid lipofuscinosis (LINCL), a subclass of NCL with an onset age of 2 to 4 years, is caused primarily by mutations in the lysosomal peptidase tripeptidyl peptidase 1, or TPP1." (PMID 25540127, 2015). "For example, the recombinant human tripeptidyl peptidase 1 enzyme (cerliponase alfa) has been delivered as the first approved therapy via ICV infusion to treat patients with neuronal ceroid lipofuscinosis type 2 (CLN2)." (PMID 40423067, 2025). "Bone marrow stem cells transduced with a lysosomal tripeptidyl peptidase-1 (TPP1) expression construct prevented retinal degeneration in a canine model with a TPP1 null mutation, a model of neuronal ceroid lipofuscinosis." (PMID 40239758, 2025). "Deficiency of TPP1 and PPT1 have been linked to the neurodegenerative lysosomal storage disease neuronal ceroid lipofuscinosis (NCL), and ARL8B also has been linked to a lysosomal storage disorder, Niemann-Pick disease type C." (PMID 39070643, 2024). "After showing functional delivery of the TPP1 in EV treated fibroblast, the authors examined intraperitoneal administration of EVs in late-infantile neuronal ceroid lipofuscinosis (LINCL) mice to study EV distribution towards the brain." (PMID 39697359, 2022). "The expression of TPP1 is developmentally controlled, reaching peak expression at 2–4 years of age, when the onset of signs and symptoms of late infantile neuronal ceroid lipofuscinosis (CLN2, LINCL) typically manifest." (PMID 33882967, 2021). "Classic late neuronal ceroid lipofuscinosis (cLINCL), also known as CLN2 disease, is caused by mutations in the TPP1 gene that encodes the soluble lysosomal enzyme tripeptidyl peptidase 1 (TPP1)." (PMID 34831035, 2021). "Variants within genes associated with Parkinson’s disease (PARK9;ATP13A2), neuronal ceroid lipofuscinosis (NCL;TPP1) and hereditary neuropathy (DNMT1) were also identified." (PMID 27217339, 2016).
neuronal ceroid lipofuscinosis (continued). "For example, we are unable to treat late infantile neuronal ceroid lipofuscinosis (LINCL), a lysosomal storage disorder in which a mutation in CLN2 (11p15) causes neurons to fail to produce enzymatically viable tripeptidylpeptidase 1 (TPP1) and store the subunit c of mitochondrial ATP synthase." (PMID 26243591, 2015).
Batten disease (36 papers, 2013 to 2025). "Neuronal ceroid lipofuscinoses type 2 (CLN2), the most common form of Batten disease, is caused by TPP1 loss of function, resulting in tripeptidyl peptidase-1 enzyme deficiency and cerebral accumulation of lipopigments." (PMID 36362641, 2022). "TPP1 protease activity appears elevated when Batten disease is caused by mutations in CLN3 indicating a common biological pathway for CLN2 and CLN3 disease." (PMID 35159273, 2022). "CLN2 Batten disease (BD) is one of a broad class of lysosomal storage disorders that is characterized by the deficiency of lysosomal enzyme, TPP1, resulting in a build-up of toxic intracellular storage material in all organs and subsequent damage." (PMID 32443895, 2020). "Tpp1 knockdown mutants exhibited increased autofluorescence, the cellular hallmark of Batten’s disease." (PMID 31100984, 2019). "In 2017, Biomarin received FDA approval for tripeptidyl peptidase 1 (cerliponase alfa) as a treatment for the underlying cause of Batten disease, the deficiency of tripeptidyl peptidase (TPP1) a lysosomal enzyme (U.S. Food Drug Administration, 2017)." (PMID 30619446, 2018). "Batten disease or Neuronal Ceroid Lipofuscinoses Type 2 (CNL2) is a neurodegenerative disease with pediatric onset that results from the deficient activity of the lysosomal enzyme tripeptidyl peptidase 1 (TPP1)." (PMID 39860010, 2025). "In Batten disease, macrophage-derived EVs carrying the enzyme TPP1 have been shown to be effective, both in vitro and in vivo models." (PMID 39860010, 2025). "Collectively, these findings underscore the potential of TPP1-loaded EVs as a viable therapeutic strategy for Batten disease, offering a multi-faceted approach to mitigate neurodegeneration." (PMID 39860010, 2025). "We generated models in HEK293T cells of known human pathogenic PTCs corresponding to a TAG stop codon in TPP1, HEXA and NPC1 genes that cause Batten disease, Tay–Sachs disease and Niemann–Pick disease type C1, respectively." (PMID 41261131, 2025). "Herein, we report the development of a novel EV-based drug delivery system for the transport of the lysosomal enzyme tripeptidyl peptidase-1 (TPP1) to treat Batten disease (BD)." (PMID 37296618, 2023). "In an in vitro model of Batten disease, it was observed that lECVsonication and lECVsaponin would result in a higher TPP1 accumulation in the damaged cells, compared to the nECVs and tECVs." (PMID 33898169, 2021). "Mφ‐derived ECVs have also been evaluated for delivery of tripeptidyl peptidase 1 (TPP1) to the lysosomal compartment of cells in the brain tissue to treat Batten disease." (PMID 33898169, 2021). "The efficacy of tripeptidyl peptidase 1 (cerliponase alfa) on the walking ability of Batten disease patients demonstrates that enzyme replacement therapy for diseases that affect the brain is theoretically possible." (PMID 30619446, 2018). "Neuronal ceroid lipofuscinoses type I and type II (NCL1 and NCL2) also known as Batten disease are the commonly observed neurodegenerative lysosomal storage disorder caused by mutations in the PPT1 and TPP1 genes respectively." (PMID 30541466, 2018). "In this context, it is important to note that we have very recently demonstrated near-complete recovery of disease symptoms in a mouse model of Batten disease by K16ApoE-mediated delivery of recombinant tripeptidyl peptidase 1(TPP1) in TPP1 knockout mice." (PMID 24847943, 2014). "We also measured α- and β-mannosidase activities in brain tissues from Dachshunds with neuronal ceroid lipofuscinosis 2 (CLN2 disease), an LSD due to lysosomal tripeptidyl peptidase-1 (TPP1) deficiency, and from a mixed breed hound with no known disease, which served as a normal control." (PMID 37761886, 2023).
Batten disease (continued). "Commonly known as Batten disease, the different subtypes are each caused by a mutation in a distinct ceroid lipofuscinosis neuronal (CLN) gene (PPT1/CLN1, TPP1/CLN2, CLN3, DNAJC5/CLN4, CLN5, CLN6, MFSD8/CLN7, CLN8, CTSD/CLN10, PGRN/CLN11, ATP13A2/CLN12, CTSF/CLN13)." (PMID 35252181, 2022). "One of this group, CLN2 Batten disease (BD), results from mutations in TPP1 gene, causing an insufficiency or complete lack of a soluble lysosomal enzyme, tripeptidyl peptidase-1 (TPP1)." (PMID 32443895, 2020). "For example, cerliponase alfa, or recombinant human tripeptidyl peptidase 1 (TPP1), is a US Food and Drug Administration (FDA)-approved ERT infused through an Ommaya reservoir to treat children with CLN2 Batten disease." (PMID 39206077, 2024). "Macrophage-derived EVs were also used for brain delivery of a soluble lysosomal enzyme tripeptidyl peptidase-1, TPP1, for the treatment of Neuronal Ceroid Lipofuscinoses 2 (CLN2) or Batten disease." (PMID 33304924, 2020).
lysosomal storage disorder (29 papers, 2012 to 2025). "CLN2 disease (neuronal ceroid lipofuscinosis type 2) is an ultra-rare lysosomal storage disorder caused by mutations in the TPP1/CLN2 gene, resulting in impaired tripeptidyl peptidase 1 (TPP1) activity." (PMID 40507848, 2025). "The neuronal ceroid lipofuscinosis type 2 (CLN2) is a heterogeneous group of neurodegenerative lysosomal storage disorders caused by autosomal recessive inheritance of two pathogenic variants in trans in the TPP1 gene." (PMID 38974612, 2024). "Several of these proteins are key lysosomal catabolizing proteins that are mutated in various lysosomal storage disorders such as Tpp1, Manba, and Naga107,119,120." (PMID 39033178, 2024). "CLN2 disease is a lysosomal storage disorder caused by mutations in the TPP1 gene, and is characterized by childhood neurodegeneration, language delay, motor abnormalities, seizures, blindness, and early death." (PMID 35745855, 2022). "CLN2 disease (Neuronal Ceroid Lipofuscinosis Type 2) is an ultra-rare, neurodegenerative lysosomal storage disease, caused by an enzyme deficiency of tripeptidyl peptidase 1 (TPP1)." (PMID 33882967, 2021). "Neuronal ceroid lipofuscinosis type 2 (CLN2) is an autosomal recessive neurodegenerative lysosomal storage disorder caused by deficient activity of the tripeptidyl peptidase 1 enzyme (TPP1)." (PMID 33377563, 2021). "Late infantile neuronal ceroid lipofuscinosis (CLN2 disease) is a rare lysosomal storage disorder caused by a monogenetic deficiency of tripeptidyl peptidase-1 (TPP1)." (PMID 30323181, 2018). "Importantly, our data also show that the splicing of the TPP1 gene deficient in another lysosomal storage disorder, cLINCL, can be improved in a minigene assay using the same substances." (PMID 34831035, 2021). "Furthermore, these substances are also capable of improving the splicing of a common TPP1 gene variant that is associated with another lysosomal storage disorder." (PMID 34831035, 2021). "Instead of proteins with chaperone or redox function, PPT1 KO lipofuscin exhibited accretion of several proteins implicated in NCLs and other lysosomal storage disorders (SAP, CATD, TPP1, SCRB2, ASAH1)." (PMID 40166029, 2025). "In fact, isolated cases with GP hypointensities consistent with iron excess are known in at least 17 distinct genes, including AP4M1 and AP4S1, which, like FUCA1, GLB1, and TPP1, are involved in lysosomal disorders." (PMID 36233161, 2022). "The Exos significantly increased the stability of TPP1 against protease degradation and provide efficient TPP1 delivery to target cells in an in vitro model of neuronal ceroid lipofuscinoses 2, a lysosomal storage disorder." (PMID 33898169, 2021). "Under pathological conditions, TPP1 immunoreactivity has been demonstrated in neurological disorders, lysosomal storage diseases, inflammation and differentiated neoplasms." (PMID 33317560, 2020). "There are several advantages for use of gemfibrozil in children with lysosomal storage diseases, NCLs, and in particular late infantile batten disease CLN2/TPP1." (PMID 28623936, 2017). "Changes in TPP1 (CLN2) and CATD (CLN10) enzyme activity with time and in CLN1 suggest coregulation of NCL proteins and a critical contribution of this lysosomal storage disorder network to natural aging processes." (PMID 40166029, 2025). "Recombinant TPP1 (cerliponase alfa) was approved for treatment of the brain in CLN2 disease, an inherited lysosomal storage disorder, and the enzyme was infused into one lateral ventricle bimonthly via an Ommaya reservoir." (PMID 35745855, 2022).
neuronal ceroid lipofuscinosis type 2 (27 papers, 2019 to 2026). "TPP1 is a lysosomal serine protease implicated in late infantile neuronal ceroid lipofuscinosis type 2 (CLN2 disease)." (PMID 41561322, 2026). "Mutations in the tripeptidyl peptidase 1 (TPP1) gene lead to neuronal ceroid lipofuscinosis type 2 (CLN2), characterized by lysosomal accumulation of lipofuscins predominantly in the brain and retina." (PMID 40706588, 2025). "Neuronal ceroid lipofuscinosis type 2 is caused by biallelic pathogenic variants of theTPP1gene, leading to a deficiency of the lysosomal tripeptidyl-peptidase 1 (TPP1) enzyme." (PMID 38763144, 2024). "Neuronal ceroid lipofuscinosis type 2 (CLN2) is an autosomal recessive neurodegenerative disease caused by variants in the TPP1 gene that lead to the deficiency of the lysosomal enzyme tripeptidyl peptidase I (TPP1) activity." (PMID 36118858, 2022). "Late-infantile neuronal ceroid lipofuscinosis type 2 (CLN2) is a neurodegenerative condition caused by biallelic TPP1 variants." (PMID 32631363, 2020). "Neuronal ceroid lipofuscinosis type 2 (CLN2 disease) is an autosomal recessive condition caused by variants in the TPP1 gene, leading to deficient activity of the lysosomal enzyme tripeptidyl peptidase I (TPP1)." (PMID 31283065, 2019). "Defective TPP1 function results in abnormal accumulation of protein and lipofuscin-like material in cells eventually leading to cell dysfunction and diseases including the neurodegenerative disease neuronal ceroid lipofuscinosis type 2 (CLN2)." (PMID 36147632, 2022). "Neuronal ceroid lipofuscinosis type 2 (CLN2; OMIM 204,500) is caused by mutations in the CLN2 gene resulting in deficient activity of the lysosomal enzyme tripeptidyl peptidase 1 (TPP1)." (PMID 35652945, 2022). "Neuronal ceroid lipofuscinosis type 2 (CLN2 disease; OMIM#204500) is an autosomal recessive disease, caused by deficiency of the lysosomal enzyme tripeptidyl peptidase (TPP1; EC 3.4.14.9)." (PMID 33990214, 2021). "One exceptional case is cerliponase alfa (BrineuraTM), a recombinant proenzyme form of human tripeptidyl peptidase-1 (TPP1) approved for treatment of neuronal ceroid lipofuscinosis type 2 (CLN2) disease via intraventricular infusion." (PMID 33066423, 2020). "Neuronal ceroid lipofuscinosis type 2 (CLN2) disease, also known as late infantile neuronal ceroid lipofuscinosis, is one of the most common NCLs and is caused by pathogenic variants in the TPP1 gene encoding the lysosomal enzyme tripeptidyl peptidase 1 (TPP1)." (PMID 33356800, 2021).